LATS1 (large tumor suppressor kinase 1)
Diseases named in the same sentence as LATS1 in open-access papers (continued):
Sharing a sentence is not in itself a finding about the gene and the disease.
adenosquamous carcinoma (1 paper, 2018). A carcinoma composed of malignant glandular cells and malignant squamous cells. "Metaplastic carcinomas are typically negative of hormone receptors (ER/PR) and HER-2/neu, and are histologically characterized by mixed epithelial and transdifferentiated components, thus resembling the adenosquamous carcinomas detected in the Lats1-CKO PyMT tumors." (PMID 30456386, 2018). "Surprisingly, a notable portion of Lats1-CKO PyMT mice developed adenosquamous carcinoma, a tumor type not observed in Lats2-CKO PyMT mice." (PMID 30456386, 2018).
adrenocortical carcinoma (1 paper, 2024). "lncRNA-ASB16-AS1 promotes ubiquitin E3 ligase BTRC-mediated ubiquitination and degradation of LATS1 to inhibit adrenocortical carcinoma cell growth." (PMID 37897508, 2024).
Alzheimer disease (1 paper, 2025). A progressive, neurodegenerative disease characterized by loss of function and death of nerve cells in several areas of the brain leading to loss of cognitive function such as memory and language. "As such, dysregulation of Hippo signaling, particularly of its core kinases MST1/2 and LATS1/2, has begun to attract attention in the Alzheimer’s disease (AD) field." (PMID 41013661, 2025).
asthma (1 paper, 2022). "The hippo signaling pathway is mainly composed of MST1/2, LATS1/2, SAV1, MOB1, YAP, or TAZ, and TEAD and is involved in ALI, PAH, pneumonia, IPF, and asthma." (PMID 35443749, 2022).
B-cell lymphomas (1 paper, 2021). "In this study in B-cell lymphomas, we also found the low mutation frequencies of the major components of Hippo pathway like LATS1 (1%), LATS2 (1%), YAP1 (1%), and FAT1 (6%)." (PMID 34926267, 2021).
brain tumour (1 paper, 2020). "Although it is generally accepted that YAP1 is the main functional output of the hippo pathway and that its dysregulation leads to tumourigenesis, it remains to be tested whether YAP1 has an essential role in Lats1/2-dependent brain tumour generation." (PMID 32404936, 2020).
breast metaplastic carcinoma (1 paper, 2018). "Notably, LATS1, but not LATS2, was down-regulated in human breast metaplastic carcinoma, which is thought to occur via transdifferentiation of a subpopulation of cancer cells." (PMID 30456386, 2018).
cardiac conduction disorders (1 paper, 2023). "Yap/Taz knockout rescued the cardiac conduction disorders observed in Lats1/2 mutant mice and reduced SAN fibrosis and fibroblast proliferation caused by Lats1/2 deficiency." (PMID 40667526, 2023). "Lats1/2 mutant mice developed cardiac conduction disorders including SND presenting lower heart rates and irregular RR intervals, and atrioventricular (AV) block indicated by 24 h spontaneous ECG recording using implanted telemetry transmitters." (PMID 40667526, 2023).
cervical tumors (1 paper, 2014). "Additionally, loss of heterozygosity of LATS1 chromosomal region predisposes to breast, ovarian, and cervical tumors." (PMID 25628642, 2014).
chordoma (1 paper, 2022). Chordomas are rare malignant tumors arising from embryonic remnants of the notochord in axial skeleton. "Five regulators of this pathway (TAOK1, TAOK2, MOB1A/B, and LATS1) were significantly suppressed in chordoma samples and two of them are predicted targets for upregulated miRNAs (TAOK1 for miR-142, and MOB1B for miR-148a and miR-182)." (PMID 36033338, 2022).
cognitive decline (1 paper, 2025). "The mice were subjected to a battery of behavioral tests at 5 months and 9 months of age to assess the effects of neuronal KO of Lats1 and Lats2 on AD‐associated cognitive decline." (PMID 40923675, 2025). "Our results indicated that 5xFAD mice with ablation of Lats1 and Lats2 were protected against cognitive decline compared with control 5xFAD mice, and this protection was correlated with a marked reduction in neurodegeneration." (PMID 40923675, 2025). "The observation that downstream Hippo signaling inhibition by KO of Lats1 and Lats2 helped to prevent cognitive decline and reduce neurodegeneration in 5xFAD mice prompted us to investigate how KO of Lats1 and Lats2 may be beneficial for the survival of neurons." (PMID 40923675, 2025).
Cognitive impairment (1 paper, 2025). Abnormal cognition is characterized by deficits in thinking, reasoning, or remembering. "To determine how inhibition of Hippo signaling might affect AD‐related cognitive impairments and pathology, we generated 5xFAD mice with conditional KO of Lats1 and Lats2 in forebrain neurons." (PMID 40923675, 2025).
COVID-19 (1 paper, 2021). A disease caused by infection with severe acute respiratory syndrome coronavirus 2. "The corresponding targets, such as TGF-βR1, SMAD-proteins, LATS1/2 and β-catenin point to further fibrotic processes that might be central to COVID-19-induced lung fibrosing lesions." (PMID 34638691, 2021).
cutaneous melanoma (1 paper, 2022). A primary melanoma arising from atypical melanocytes in the skin. "For example, >80% of uveal melanomas and ~6% of cutaneous melanomas have mutations in GNAQ/GNA1 proteins, which stimulate RhoA activity and activate YAP/TAZ independent of any alterations in LATS1/272–74." (PMID 35768444, 2022).
cystadenoma (1 paper, 2019). A benign or borderline cystic epithelial neoplasm arising from the glandular epithelium. "LATS1/2 protein expression was significantly different (p < 0.001) among the tumor types: it was lowest in cystadenoma, intermediate in carcinoma, and highest in borderline." (PMID 31586262, 2019). "Taken together, LATS1/2 protein expression was higher in carcinomas than in cystadenomas, was higher in serous than in mucinous cancers, and was FIGO stage independent." (PMID 31586262, 2019). "LATS1/2 expression was lowest in cystadenoma, intermediate in carcinoma, and highest in borderline." (PMID 31586262, 2019).
dementia (1 paper, 2022). Loss of intellectual abilities interfering with an individual's social and occupational functions. "It will be interesting to further investigate the roles of LATS1, MST2, Nanog and SREBP1 in aging and the development of dementia." (PMID 36138870, 2022).
dermal tumors (1 paper, 2022). "We observed that BrafV600E/Lats1/2−/− mice were highly prone to developing spontaneous dermal tumors within weeks after birth, even without topical 4-hydroxytamoxifen (4-HT) administration." (PMID 35768444, 2022).
Duchenne muscular dystrophy (1 paper, 2022). Duchenne muscular dystrophy (DMD) is a neuromuscular disease characterized by rapidly progressive muscle weakness and wasting due to degeneration of skeletal, smooth and cardiac muscle. "The reanalysis of published datasets also revealed that LATS1 expression is 63% higher in the quadriceps of young boys with Duchenne muscular dystrophy compared to healthy quadriceps muscle." (PMID 34984591, 2022).
ductal carcinoma in situ (1 paper, 2022). "Upon Tamoxifen-induced deletion of LATS1/2 in this model, we observed a dramatic overgrowth of cells within the mammary ducts, leading to a phenotype resembling ductal carcinoma in situ (DCIS)." (PMID 36443313, 2022).
gastric tumor (1 paper, 2022). "In this study, clinical gastric tumor samples, cell-based experiments, and nude mouse models were employed to provide the first evidence that FBXW5 binds to and degrades LATS1 through the ubiquitin-proteasome pathway, ultimately inactivating the Hippo signaling pathway." (PMID 35210431, 2022).
head and neck cancer (1 paper, 2025). A primary or metastatic malignant neoplasm affecting the head and neck. "For example, EGFR activation, which is commonly observed in head and neck cancer, promotes tyrosine phosphorylation of MOB1 and subsequently inhibits LATS1/2 activity." (PMID 40486910, 2025). "For example, the EGFR signaling pathway is frequently abnormally active in head and neck cancer; its effects may be partly mediated by interfering with MOB1-dependent LATS1/2 activation in synergy with TAO kinase upregulation, collectively promoting YAP/TAZ activation." (PMID 40486910, 2025).
Hearing impairment (1 paper, 2025). A decreased magnitude of the sensory perception of sound. "When LATS1 function is compromised, it can lead to the aberrant activation of YAP/TAZ, resulting in cell cycle disruption and increased apoptosis, which may ultimately contribute to hearing impairment." (PMID 40001646, 2025).
hepatic diseases (1 paper, 2016). "Remarkably, Lats1/2-deficient livers show severe fibrosis accompanied with the ductal reaction associated with various hepatic diseases." (PMID 27358050, 2016).
Hepatic steatosis (1 paper, 2019). Steatosis is a term used to denote lipid accumulation within hepatocytes. "In diet‐induced diabetic mice, either Lats1 overexpression or YAP knockdown protects against hepatic steatosis and hyperlipidaemia through suppression of the interaction between YAP and SREBP‐1c/SREBP‐2." (PMID 30821074, 2019).
hepatoblastoma (1 paper, 2023). Hepatoblastoma (HB) is a malignant hepatic tumor and is the most common pediatric liver cancer. "The tumor suppressive genes (Taok1, Lats1, Nf2), upstream of the Hippo pathway that inhibit YAP through phosphorylation-induced cytoplasmic retention and degradation, are important for hepatoblastoma proliferation." (PMID 37414763, 2023).
influenza infection (1 paper, 2026). "STAT1 was dispensable for IFN-mediated LATS1 phosphorylation and suppression of tissue repair, although as expected STAT1 was required for IFN-mediated protection from rhinovirus or influenza infection." (PMID 41587178, 2026).
intracranial hypertension (1 paper, 2024). A finding characterized by increased cerebrospinal fluid pressure within the skull. "Intracranial hypertension also increased the expression of p‐LATS1 and p‐YAP, which was partially prevented by GsMTx4." (PMID 39328029, 2024). "Intracranial hypertension also increased the expression of p‐LATS1 and p‐YAP, which was partially prevented by Piezo1 knockdown." (PMID 39328029, 2024).
lupus nephritis (1 paper, 2024). Glomerulonephritis in the context of systemic lupus erythematosus. "Interestingly, the expression of LATS2 but not LATS1 was significantly downregulated in lupus nephritis specimens, especially in proximal tubules." (PMID 38459604, 2024).
mantle cell lymphoma (1 paper, 2018). Mantle cell lymphoma is a rare form of malignant non-Hodgkin lymphoma affecting B lymphocytes in the lymph nodes in a region called the ``mantle zone''. "Moreover, in the group of 36 mantle-cell lymphoma patients decreased LATS1 expression correlated with PFS and OS." (PMID 29850494, 2018).
meningioma (1 paper, 2020). A generally slow growing tumor attached to the dura mater. "Then, we analysed Hippo pathway activation, showing that MLN3651 increased LATS1/2 expression in meningioma cells after 4 hours, suggesting CRL4-DCAF1 inhibition." (PMID 32629964, 2020).
myeloid leukemia (1 paper, 2009). A clonal proliferation of myeloid cells and their precursors in the bone marrow, peripheral blood, and spleen. "We analyzed Lats1 mRNA expression in 4 mammary gland tumors, 2 uterine tumors and 3 spleens from mice suffering from MLPD-like myeloid leukemias." (PMID 19656388, 2009).
nasopharyngeal carcinoma (1 paper, 2025). A carcinoma arising from the nasopharyngeal epithelium. "In nasopharyngeal carcinoma, miR-424-5p (miR-424 mature miRNA) has been shown to facilitate tumor growth, migration, and angiogenesis by targeting large tumor suppressor kinase 1 (LATS1), a key regulator of the Hippo signaling pathway." (PMID 39866229, 2025).
nephrotic syndrome (1 paper, 2025). A collection of symptoms that include severe edema, proteinuria, and hypoalbuminemia; it is indicative of renal dysfunction. "Furthermore, we selected 3 NPH1 patients and 3 control patients with primary nephrotic syndrome and found that phosphorylated MST1/2, LATS1 and YAP levels in renal tissue were higher in NPH1 patients than in nephrotic syndrome patients." (PMID 39995111, 2025).
neurofibroma (1 paper, 2025). An intraneural or extraneural neoplasm arising from nerve tissues and neural sheaths. "Chen and colleagues reported that the activation of Yap in Schwann cells through knockout of Lats1 and Lats2 drove neurofibroma formation in mice when combined with Nf1 loss, which drives MAPK signaling." (PMID 39804140, 2025).
Obesity (1 paper, 2022). Accumulation of substantial excess body fat. "We thus investigated whether Lats1/2 deficiency could exacerbate fat tissue fibrosis in the context of obesity that provides endogenous TGFβ signal." (PMID 36229481, 2022). "Lats1 and Lats2 mRNA were upregulated in both obesity models." (PMID 36229481, 2022).
oligodendroglioma (1 paper, 2021). A well-differentiated (WHO grade II), diffusely infiltrating neuroglial tumor, typically located in the cerebral hemispheres. "Inactivation of LATS1 and LATS2 would be associated with more aggressive tumours, and with a poorer prognosis, with the exception of oligodendrogliomas, for which hypermethylation of the LATS2 promoter predicts a better survival, as observed in CRC." (PMID 34885067, 2021).
oral cancers (1 paper, 2019). "Consistent with this, in many human malignant tumors, such as liver, colon, breast, and oral cancers, YAP/TAZ are activated, whereas LATS1/2 are inactivated." (PMID 30800215, 2019).
ovarian breast cancer (1 paper, 2022). "Similar findings have been reported for ovarian breast cancer cells, indicating that this response may be conserved among distinct cancer types and, in agreement with our study, the Hippo pathway kinase Lats1 was not involved." (PMID 36077517, 2022).
pituitary carcinomas (1 paper, 2019). A primary or metastatic malignant neoplasm affecting the pituitary gland. "Although human pituitary carcinomas are only diagnosed as such after metastasis, the tumours generated in our LATS1/2 mouse models fit their histopathological profile." (PMID 30912742, 2019).
pterygium (1 paper, 2016). A wedge-shaped fibrovascular lesion arising from the bulbar conjunctiva and extending to the cornea. "Further studies are required to identify the exact molecular function of LATS1/LATS2 genes in pterygium in various and larger genetic populations using advanced molecular techniques." (PMID 26942001, 2016). "Promoter methylation of LATS1 and LATS2 was detected significantly between pterygium tissues and normal tissues [LATS1; OR = 4.9; 95% CI: 1.54 to 15.48, P = 0.003; LATS2; OR = 7.1; 95% CI: 1.53 to 33.19, P = 0.004]." (PMID 26942001, 2016). "Therefore, silencing of LATS1 and LATS2 putative tumor suppressor genes through promoter methylation may cause the development of pterygium." (PMID 26942001, 2016). "The data of this study is the first report regarding the effect of promoter methylation of the LATS1 and LATS2 in the pterygium." (PMID 26942001, 2016).
renal fibrosis (1 paper, 2025). A final common manifestation of a wide variety of chronic kidney diseases characterized by glomerulosclerosis and tubulointerstitial fibrosis. "In our study of UUO-induced renal fibrosis, inhibiting EZH2 with ZLD1039 restored LATS1 expression at both 7 and 14 days, indicating that LATS1 plays a protective role in renal fibrosis." (PMID 40478495, 2025). "Significant progresses have been made in understanding the upstream mechanisms of the Hippo-YAP signaling pathway, yet the specific role of LATS1 in renal fibrosis remains unknown." (PMID 40478495, 2025). "In summary, the initial EZH2-mediated reduction in LATS1 likely contributes, at least in part, to YAP activation in UUO-induced renal fibrosis." (PMID 40478495, 2025). "Mechanically, our study identifies ZLD1039 as a potential anti-fibrotic therapeutic agent that attenuates renal fibrosis by inhibiting EZH2/H3K27me3 and up-regulating LATS1, thereby preventing YAP nuclear translocation." (PMID 40478495, 2025). "Importantly, ZLD1039 enhanced LATS1 transcription and up-regulated its phosphorylation level, subsequently increasing YAP phosphorylation, thereby ameliorating renal fibrosis." (PMID 40478495, 2025). "Importantly, we propose that EZH2 and H3K27me3 inhibit LATS1 expression and activation, leading to reduced p-YAP levels and promoting YAP nuclear translocation, thereby regulating renal fibrosis." (PMID 40478495, 2025). "Not surprisingly, the mRNA expression level of LATS1 was dramatically decreased in rats with UUO-induced renal fibrosis." (PMID 40478495, 2025).
sarcomatoid carcinoma (1 paper, 2022). A malignant epithelial neoplasm characterized by the presence of spindle cells and anaplastic morphologic features. "Concordantly, these tumors displayed markedly different histologies; whereas WT luminal cells generated poorly differentiated carcinomas, Lats1-CKO luminal cells generated basal-like sarcomatoid carcinomas." (PMID 36443319, 2022).
spinal meningioma (1 paper, 2022). Spinal meningioma isa rare type of spinal cord cancer. "In spinal schwannoma, one study reported a mutation in the large tumor suppressor kinase 1 gene (LATS1), a downstream mediator of NF2, but the clinical relevance of these alterations remains unknown in spinal meningiomas." (PMID 36713513, 2022).
sterility (1 paper, 2022). "For Hippo pathway genes, LATS1 deficiency in mice causes sterility and ovarian tumourigenesis, while LATS1 regulates the activity of FOXL2, which is a defective gene in some POI patients." (PMID 36017238, 2022).
thymoma (1 paper, 2025). A neoplasm arising from the epithelial cells of the thymus. "Positive LATS1 lymphocytes were mostly observed in B1-B2 thymomas as well as in AB thymomas (Fisher’s exact test, p < 0.001)." (PMID 40649713, 2025). "Accordingly, cytoplasmic MST1 expression as well as nuclear and cytoplasmic LATS1 expression were significantly higher in TCs and B3 thymomas." (PMID 40649713, 2025).
ulcerative colitis (1 paper, 2021). An inflammatory bowel disease involving the mucosal surface of the large intestine and rectum. "Mechanically, miR-590-3p targets large tumor suppressor kinase 1 (LATS1) and then activates the Yes-associated protein (YAP)/β-catenin pathway, thereby reducing inflammatory release, improving wound healing ability of epithelial cells, and alleviating ulcerative colitis." (PMID 34249713, 2021).